LGALS12 (galectin 12)
Description:
Binds lactose. May participate in the apoptosis of adipocytes.
Synonyms: GRIP1; GAL12
Tractability: PROTAC: ubiquitination databases record sites on it.
Gene: Protein-coding gene on chromosome 11 (63,506,052 to 63,519,767, forward strand). Ensembl gene ENSG00000133317.
Subcellular location: Nucleus
Subcellular location (Human Protein Atlas): Cytosol
Gene Ontology:
Molecular function: lactose binding; carbohydrate binding
Biological process: intrinsic apoptotic signaling pathway
Cellular component: cytoplasm; mitochondrion; nucleus
Genetic constraint (gnomAD): Loss-of-function variants: 35 observed, 36.54 expected, observed/expected ratio (o/e) 0.96, 90% interval 0.73 to 1.27. The upper end of that interval is the gene's LOEUF score, 1.27, which puts it in group 5 of 6, group 1 being the genes least tolerant of losing a copy. Missense variants: 361 observed, 409.22 expected, observed/expected ratio (o/e) 0.88, 90% interval 0.81 to 0.96. Synonymous variants: 144 observed, 163.09 expected, observed/expected ratio (o/e) 0.88, 90% interval 0.77 to 1.01.
Homologues: Orthologues: chimpanzee LGALS12 (99% identical), macaque LGALS12 (93% identical), pig LGALS12 (87% identical), dog LGALS12 (85% identical), rat Lgals12 (82% identical), guinea pig LGALS12 (82% identical), mouse Lgals12 (81% identical), rabbit LGALS12 (81% identical), Caenorhabditis elegans lec-12 (24% identical), Drosophila melanogaster galectin (24% identical), Caenorhabditis elegans F40H6.5 (22% identical), Caenorhabditis elegans lec-1 (22% identical), and 18 more. Paralogues in human: LGALS9B (31% identical), LGALS9 (30% identical), LGALS9C (30% identical), LGALS4 (30% identical), LGALS8 (29% identical), LGALS3 (16% identical), LGALSL (14% identical), LGALS7 (11% identical), LGALS7B (11% identical), LGALS1 (10% identical), LGALS14 (7% identical), LGALS2 (7% identical), and 4 more.
Diseases named in the same sentence as LGALS12 in open-access papers:
LGALS12 is named in the same sentence as 32 diseases in open-access papers, as found by Europe PMC text mining. Sharing a sentence is not in itself a finding about the gene and the disease. The quoted sentences say what the papers report.
acute myeloid leukemia (5 papers, 2018 to 2025). Acute myeloid leukemia (AML) is a group of neoplasms arising from precursor cells committed to the myeloid cell-line differentiation. "Among lipid metabolism inhibitors, galectin-12 was found to have a role in modulating LD production in acute myeloid leukemia in vitro." (PMID 38137407, 2023). "In acute myeloid leukemia, the expression level of galectin-12 is downregulated (88.7% downregulation compared to normal controls) and patients with lower galectin-12 levels have a lower survival rate compared to those with higher galectin-12 levels." (PMID 29316658, 2018).
Obesity (5 papers, 2016 to 2025). Accumulation of substantial excess body fat. "Galectin-12 has two CRDs separated by a linker sequence and is preferentially expressed in adipocytes, whose dysfunctions links obesity to insulin resistance and type 2 diabetes." (PMID 27073999, 2016). "Hence, galectin-12 is a possible target for therapies to reduce obesity and diabetes mellitus (type 2)." (PMID 29950926, 2018). "Targeting galectin-12 is interesting as it is fat tissue specific and therefore targeting it could help in the prevention/treatment of obesity and diabetes in a targeted manner where other processes, such as cancer, maybe are not affected." (PMID 29950926, 2018). "The regulation of galectin-12 stability by VPS13C could potentially be exploited for therapeutic intervention of obesity and related metabolic diseases." (PMID 27073999, 2016). "In another integrative methylome–transcriptome analysis, seven key genes were identified—CCRL2, GPT, LGALS12, PC, SLC27A2, SLC4A4, and TTC36—that were hypermethylated in obesity and concurrently showed reduced expression." (PMID 41303351, 2025). "In summary, we successfully identified seven key genes, namely, CCRL2, GPT, LGALS12, PC, SLC27A2, SLC4A4, and TTC36, which are involved in obesity occurrence and development likely through the immune microenvironment." (PMID 36313453, 2022). "In this study, by analyzing three GEO datasets and verifying in 24 patients, we identified that CCRL2, GPT, LGALS12, PC, SLC27A2, SLC4A4, and TTC36 might be the key genes that play an important role in obesity pathogenesis." (PMID 36313453, 2022).
acute promyelocytic leukemia (3 papers, 2020 to 2025). An aggressive form of acute myeloid leukemia (AML), characterized by arrest of leukocyte differentiation at the promyelocyte stage, due to a specific chromosomal translocation t(15;17) in myeloid cells. "Moreover, galectin-12 expression is particularly abundant in AML samples classified as FAB subtype M3, corresponding to acute promyelocytic leukemia, as emerged from public datasets." (PMID 38137407, 2023).
atherosclerosis (3 papers, 2020 to 2023). A disease characterized by the build-up of fatty material and calcium deposition in the arterial wall resulting in partial or complete occlusion of the arterial lumen. "Galectin-12 deficiency in mice leads to M2 macrophage polarization that consequently reduced foam cell formation and pro-inflammatory cytokine production thereby reducing atheroma formation in an atherosclerosis animal model." (PMID 36873388, 2023). "Based on these results, we propose galectin-12 as a potential therapeutic target for atherosclerosis." (PMID 32752134, 2020). "Based on these results, it was proposed that inhibition of galectin-12 may be a novel therapeutic strategy to slow down the progression of atherosclerosis." (PMID 36873388, 2023). "In this study, we found lower levels of plasma leptin in Gal12‒/‒ mice, suggesting that the ablation of galectin-12 may have a protective benefit against atherosclerosis." (PMID 32752134, 2020). "We found significantly lower foam cell formation in Gal12‒/‒ compared to Gal12+/+ macrophages, indicating that galectin-12 ablation may indeed be beneficial in the pathogenesis of atherosclerosis." (PMID 32752134, 2020). "Together, the results revealed lower foam cell formation in Gal12−/− BMDM indicating that the inhibition of galectin-12 may be beneficial in the treatment of atherosclerosis." (PMID 32752134, 2020). "To determine whether galectin-12 may be involved in the pathogenesis of atherosclerosis, we measured leptin concentration in the sera of galectin-12 wild type (Gal12+/+) and knockout (Gal12−/−) mice." (PMID 32752134, 2020). "Thus, we sought to clarify the mechanisms whereby galectin-12 participates in the pathogenesis of atherosclerosis." (PMID 32752134, 2020). "This prompted us to study the role of galectin-12 in atherosclerosis." (PMID 32752134, 2020). "Therefore, we propose that inhibition of galectin-12 could be used as a therapeutic strategy to slow down the progression of atherosclerosis." (PMID 32752134, 2020). "However, it remains unknown whether galectin-12 knockout could ameliorate atherosclerosis through the downregulation of chronic inflammation." (PMID 32752134, 2020). "In a previous study, we found that the ablation of galectin-12 decreased the secretion of MCP-1, TNF-α, and IL-6 in lipopolysaccharide (LPS)—and saturated fatty-acid-stimulated macrophages, suggesting that galectin-12 may potentially play a role in the pathogenesis of atherosclerosis." (PMID 32752134, 2020). "Moreover, the ablation of galectin-12 decreased atherosclerosis formation in DKO mice." (PMID 32752134, 2020). "Then, we generated an LDL receptor and galectin-12 double knockout (DKO) mice and studied the effect of galectin-12 on macrophage function and atherosclerosis." (PMID 32752134, 2020). "Ablation of galectin-12 decreased the secretion of MCP-1, TNF-α, and IL-6 in LPS- and saturated fatty-acid-stimulated macrophages, suggesting the involvement in the pathogenesis of atherosclerosis." (PMID 36873388, 2023). "Previously, we found that knocking down galectin-12, a negative regulator of lipolysis, leads to reduced secretion of monocyte chemoattractant protein-1 (MCP-1), a chemokine that plays an important role in atherosclerosis." (PMID 32752134, 2020).
diabetes (3 papers, 2018 to 2023). "Lgals12−/− mice have increased insulin sensitivity and glucose tolerance, contributing galectin-12 function to diabetes and metabolic syndrome, and indicating the potential involvement in cardiovascular diseases." (PMID 36873388, 2023). "Targeted disruption of Gal-12 gene (Lgals12) in mice increased insulin sensitivity and glucose tolerance and contributed to diabetes and metabolic syndrome, suggesting the potential role of this lectin in cardiovascular diseases." (PMID 30524200, 2018). "For galectin-1 and galectin-9, an increase in the levels of the proteins could protect against diabetes, whilst for galectin-12 inhibition of the protein could be protective." (PMID 29950926, 2018).
Insulin resistance (3 papers, 2016 to 2024). Increased resistance towards insulin, that is, diminished effectiveness of insulin in reducing blood glucose levels. "Ablation of galectin-12 reduces adiposity and alleviates glucose intolerance and insulin resistance associated with weight gain." (PMID 27073999, 2016).
metabolic syndrome (3 papers, 2018 to 2023). A cluster of metabolic risk factors for CARDIOVASCULAR DISEASES and TYPE 2 DIABETES MELLITUS. "Thus, galectin-12, resistin, leptin, and other adipokines/cytokines regulated by PPARγ may act synergistically to affect lipid metabolism in metabolic tissues, contributing to the dyslipidemia associated with APL." (PMID 32929351, 2020).
acne (1 paper, 2025). An inflammatory process of the sebaceous glands which is characterized by comedones, nodules, papules and/or pustules on the skin. "Given the central role of galectin-12 in sebaceous gland function and its potential involvement in skin disorders such as acne, seborrheic dermatitis, and sebaceous gland hyperplasia, galectin-12 is emerging as a promising therapeutic target." (PMID 40563477, 2025).
atopic dermatitis (1 paper, 2025). "Moreover, galectin-12 KO mice demonstrated reduced skin inflammation in a mouse model of atopic dermatitis induced by repeated epicutaneous ovalbumin (OVA) application, as evidenced by a decrease in epidermal thickening and eosinophil infiltration." (PMID 40563477, 2025). "Given that both galectin-12 knockdown and PPARγ inhibition (GW9662) lead to reduced CCL26 expression and improved atopic dermatitis symptoms galectin-12 might sustain Th2 immune responses by reinforcing PPARγ activation in sebocytes." (PMID 40563477, 2025).
breast carcinoma (1 paper, 2012). "In breast cancer, LGALS12 has been found downregulated in the malignant tissue." (PMID 22768131, 2012).
gestational diabetes (1 paper, 2025). Carbohydrate intolerance first diagnosed during pregnancy. "Galectin-12 expression in placental tissue from women with gestational diabetes mellitus (GDM) was significantly elevated in the nucleus of syncytiotrophoblasts and extravillous trophoblasts, linking it to inflammatory processes and GDM-related complications." (PMID 40563477, 2025).
Lymphadenopathy (1 paper, 2023). Enlargement (swelling) of a lymph node. "Here, our results showed a significant association between the promoter methylation status of galectin-12 & splenomegaly, hepatomegaly and lymphadenopathy." (PMID 36861129, 2023).
nonalcoholic fatty liver disease (1 paper, 2025). "In the liver, it regulates the polarization of Kupffer cells; galectin-12 deficiency promotes M2 macrophage polarization, leading to increased TGF-β1 secretion and liver fibrosis, thereby contributing to the progression of nonalcoholic fatty liver disease (NAFLD)." (PMID 40563477, 2025).
steatosis (1 paper, 2018). Increased lipid within the cytoplasm of cells. "In our previous study, we found a very low level of galectin-12 in normal hepatocytes, but an increase in galectin-12 in the liver of C57BL/6J mice with steatosis induced by high-fat diet." (PMID 29316658, 2018).
type-2 diabetes (1 paper, 2019). "Expression of LGALS12 in adipocytes is up-regulated by PPAR-γ agonists suggesting its role in insulin signaling and type-2 diabetes." (PMID 31167428, 2019).
cancer (4 papers, 2012 to 2025). A tumor composed of atypical neoplastic, often pleomorphic cells that invade other tissues. "Beyond its established role in lipid droplets, galectin-12 has also been implicated in broader metabolic networks within cancer cells." (PMID 40563477, 2025). "Galectin-12 restricts glutamine anaplerosis by reducing uptake and impacting biomass synthesis, though cancer cells compensate under low-glutamine conditions." (PMID 40563477, 2025). "LGALS12 is a candidate tumor suppressor that is able to arrest the cell cycle and inhibit the proliferation of several cancer cell lines." (PMID 22768131, 2012).
dermatosis (2 papers, 2023 to 2025). "Galectin-12 Modulates Sebocyte Differentiation and Lipid Metabolism. sebaceous glands are responsible for producing sebum, a lipid-rich substance that plays a crucial role in skin hydration and protection; dysregulated lipid production in these glands can lead to skin disorders." (PMID 40563477, 2025).
metabolic disorders (2 papers, 2016 to 2023). "We envisage that the discovery of this novel pathway of galectin-12 regulation by VPS13C could open up novel avenues for the treatment of metabolic disorders." (PMID 27073999, 2016).
infectious disease (1 paper, 2023). A disorder directly resulting from the presence and activity of a microbial, viral, or parasitic agent in humans. "Little is known regarding the involvement of galectin-12 in infectious disease, although it has been associated with inflammation." (PMID 36977257, 2023).
LGALS12 also shares sentences with these, for which no sentence is quoted: tumor (4 papers); cardiovascular diseases (3); colon cancer (2); acute lymphoblastic leukemia (1); Arthritis (1); Genetic obesity (1); Glucose intolerance (1); infection (1); ovarian carcinoma (1); prostate carcinoma (1); psoriasis (1); seborrheic dermatitis (1); Splenomegaly (1).